PSMC6 (proteasome 26S subunit, ATPase 6)
Diseases named in the same sentence as PSMC6 in open-access papers:
PSMC6 is named in the same sentence as 34 diseases in open-access papers, as found by Europe PMC text mining. Sharing a sentence is not in itself a finding about the gene and the disease. The quoted sentences say what the papers report.
lung adenocarcinoma (8 papers, 2020 to 2025). A carcinoma that arises from the lung and is characterized by the presence of malignant glandular epithelial cells. "Studies have shown that PSMC6 is associated with lung adenocarcinoma, breast cancer, pheochromocytoma, low-grade glioma, colorectal melanoma and other diseases." (PMID 35574315, 2022). "In the present study, we investigated the clinical and functional relevance of PSMC6 in lung adenocarcinoma (LUAD) and explored its underlying mechanism in the initiation and progression of LUAD." (PMID 34239933, 2021). "PSMD13 expression in lung adenocarcinoma strongly correlates with PSMC6 expression, which is associated with poor tumor differentiation and might act as a therapeutic target in lung adenocarcinoma." (PMID 35873494, 2022). "First, in the GSE46539 lung adenocarcinoma cohort, the expression level of PSMC6, SMOX, and SMS was higher in the tumor samples than in the normal samples, which was consistent with the previous result in TCGA lung cancer samples." (PMID 38650895, 2024). "In lung adenocarcinoma, PSMC6 was found upregulated as compared to normal adjacent tissues 31, 32 - an observation that reflects our results on levels in normal ovarian and tumor cells - and PSMC6 silencing reduced the growth, migratory and invasive abilities of lung cancer cells." (PMID 40083690, 2025). "The proteasome has been validated as an anticancer drug target, while the role of a subunit of proteasome, PSMC6, in lung adenocarcinoma (LUAD) has not been fully unveiled." (PMID 34239933, 2021).
breast carcinoma (6 papers, 2020 to 2022). "Six hub genes (PSMC6, AURKB, CASP9, BAD, ZNF24, and SSX2IP) that were significantly associated with the prognosis of breast cancer." (PMID 36199443, 2022). "We then identified six hub genes (PSMC6, AURKB, CASP9, BAD, ZNF24, and SSX2IP) that were significantly associated with the prognosis of breast cancer." (PMID 36199443, 2022). "According to our results from an Oncomine analysis of mRNA expressions of PSMC2, PSMC3, PSMC4, PSMC5, and PSMC6, these members are highly upregulated in breast cancer tissues; therefore, we chose breast cancer to perform further bioinformatics analyses." (PMID 34329194, 2021). "The present findings showed significantly higher expression profiles of PSMC2, PSMC3, PSMC4, PSMC5, and PSMC6 in breast cancer compared to normal breast tissues." (PMID 34329194, 2021). "Both mRNA and protein levels of PSMC2, PSMC3, PSMC4, PSMC5, and PSMC6 were significant in cancer tissues, and PSMC1, PSMC3, PSMC4, PSMC5, and PSMC6 overexpression was associated with poor prognoses of breast cancer patients." (PMID 34329194, 2021). "Meanwhile, we discovered that high levels of PSMC1, PSMC3, PSMC4, PSMC5, and PSMC6 transcripts were positively correlated with poor survival, which likely shows their importance in breast cancer development." (PMID 34329194, 2021). "To further clarify the interaction between DEGs, we screened fifteen hub genes by constructing the PPI network, among which the expression of PSMC6, AURKB, CASP9, BAD, ZNF24, and SSX2IP was associated with OS in breast cancer patients, which attracted our attention." (PMID 36199443, 2022). "Indeed, PSMC2, PSMC3, PSMC4, PSMC5, and PSMC6 were recently reported as highly expressed in breast cancer, which correlated with worse outcomes." (PMID 36498916, 2022). "The Kaplan–Meier plotter database also showed that PSMC1, PSMC3, PSMC4, PSMC5, and PSMC6 had high expression levels in breast cancer tissues may have oncogenic roles in breast cancer progression." (PMID 34329194, 2021). "PSMC6-coexpressed genes were involved in calcium- and hormone-related pathways and networks such as “Signal transduction_Calcium-mediated signaling” and “Reproduction_Gonadotropin-releasing hormone (GnRH) signaling ”, which could participate in breast cancer." (PMID 34329194, 2021). "Of note, this does not exclude the possibility that other genes including UBB (Ubiquitin B), PSMC6 (Proteasome 26S subunit, ATPase 6), PEN1 (Penetration 1), HIST1H2BB (Histone Cluster 1 H2B Family Member B) would also play a role in the development of breast cancer." (PMID 34386417, 2021).
multiple myeloma (4 papers, 2019 to 2022). "A CRISPR genome-wide screen identified dependence on PSMC6 for bortezomib sensitivity in multiple myeloma." (PMID 36498916, 2022). "Consistently, PSMC6 was also identified as a target for bortezomib sensitivity in multiple myeloma by CRISPR genome-wide screening." (PMID 34239933, 2021). "Both the PSMC6 and MAPK8 genes were upregulated in melanosis coli patients, and CRISPR Genome-Wide Screening demonstrated that the PSMC6 subunit is an important and sensitive target for bortezomib in multiple myeloma cells." (PMID 34329194, 2021). "In human multiple myeloma cells, lacking the PSMC6 expression might induce resistance to apoptosis." (PMID 30559147, 2019).
glioma (3 papers, 2020 to 2022). A benign or malignant brain and spinal cord tumor that arises from glial cells (astrocytes, oligodendrocytes, ependymal cells). "The mRNA expression of CANX, HSPA1B, PSMC6, and TAP1 was high in gliomas, whereas that of KLRC2 was low." (PMID 32351547, 2020).
lung carcinoma (3 papers, 2021 to 2025). "Furthermore, the silence of PSMC6 by small interference RNAs (siRNAs) could significantly inhibit cell growth, migration, and invasion in lung cancer cell lines, suggesting that PSMC6 might serve as a promising therapeutic target in LUAD." (PMID 34239933, 2021). "Moreover, the silence of PSMC6 by siRNA could significantly inhibit cell growth, migration, and invasion in lung cancer cell lines." (PMID 34239933, 2021).
ovarian carcinoma (3 papers, 2020 to 2025). A malignant neoplasm originating from the surface ovarian epithelium. "CRISPR/Cas9 loss-of-function screen revealed a relationship between the PSMC6 proteasome subunit expression and survival of cisplatin-sensitive and -resistant ovarian carcinoma cells." (PMID 40083690, 2025). "Since PSMC6 expression was enhanced in tumor versus normal cells and was found to be associated with progression-free survival, PSMC6 role was further addressed in ovarian cancer cells using a functional approach based on RNA interference in 2D and 3D preclinical models." (PMID 40083690, 2025). "Overall, a link between PSMC6 and ovarian carcinoma aggressiveness is envisioned, highlighting PSMC6 as a potential diagnostic and therapeutic target." (PMID 40083690, 2025). "We also carried out an analysis of PSMC6 expression in ovarian carcinoma clinical specimens in which we observed that earlier stage disease tended to display higher PSMC6 levels, suggesting to explore approaches for targeting PSMC6 in early-stage tumors." (PMID 40083690, 2025). "In conclusion, the results obtained in this study support that PSMC6 plays a major role in the survival of ovarian carcinoma cells particularly in cisplatin-resistant cells of the endometrioid histotype, through a modulation of the MAPK pathways." (PMID 40083690, 2025). "Taken together, our results indicate that PSMC6 targeting impairs the proliferation and survival abilities of ovarian cancer cells and diminishes drug resistance through the canonical MAPK pathway." (PMID 40083690, 2025). "We subsequently evaluated specimens from ovarian carcinoma patients (n= 134) for PSMC6 mRNA levels." (PMID 40083690, 2025). "To further explore the phenotypic changes occuring upon PSMC6 knockdown in ovarian carcinoma cells, we used an antibody array approach in PSMC6-silenced IGROV-1/Pt1 and IGROV-1 cells to identify perturbations of factors implicated in cell growth and apoptosis induction." (PMID 40083690, 2025). "Thus, PSMC6 contributes to maintain the growth/survival of ovarian carcinoma cells." (PMID 40083690, 2025). "An analysis of the impact of PSMC6 knockdown in additional drug-resistant ovarian carcinoma cell lines indicated a lack of sensitization to cisplatin in models other than IGROV-1/Pt1." (PMID 40083690, 2025). "First, we evaluated the expression levels of the six PSMC family members in 24 types of cancer in TCGA database and found that PSMC5 was the most predominant in all types of cancer except ovarian cancer, whereas PSMC2 and PSMC6 had a relatively lower expression level in pan-cancer." (PMID 36699466, 2022).
Epstein-Barr virus infection (2 papers, 2020 to 2023). An infection that is caused by Epstein-Barr virus. "Specifically, SIRT6 was enriched in thermogenesis, while PSMD14 and PSMC6 were enriched in Epstein-Barr virus infection, and NCBP2 and PYM1 were enriched in nucleocytoplasmic transport." (PMID 37958518, 2023).
adenoma (1 paper, 2021). A neoplasm arising from the epithelium. "Moreover, the PSMC6 was also observed to have higher expression levels in some histology subtypes such as adenomas/adenocarcinomas and solid tumor subtypes." (PMID 34239933, 2021). "Among the three disease types, LUAD with adenomas and adenocarcinomas had a higher RNA expression of PSMC6 than the other two disease types (Kruskal-Wallis test, p value < 0.001), indicating that LUAD with the disease type of adenomas and adenocarcinomas might have a higher degree of malignancy." (PMID 34239933, 2021).
Anxiety (1 paper, 2021). Intense feelings of nervousness, tension, or panic often arise in response to interpersonal stresses. "The results indicated that Atp6v1f, Arpc5, Adcyap1r1, Ndufb6, and Psmc6 were distinctly dysregulated in the hypothalamus of the depression-susceptible group, while Gys1, Pgp, Klc1, Chka, Ncstn, Ndufa6, and Kyat1 were distinctly dysregulated in the anxiety-susceptible group." (PMID 33737865, 2021).
depression (1 paper, 2021). "The expressions of Atp6v1f, Arpc5, Ndufb6, and Psmc6 were significantly down-regulated while Adcyap1r1 was up-regulated in the depression-susceptible group compared with the control group." (PMID 33737865, 2021).
diabetes (1 paper, 2020). "On the other hand, ARL6IP1 and PSMC6 have been associated with insulin synthesis and pathology of diabetes, respectively." (PMID 32296077, 2020).
esophageal cancer (1 paper, 2021). A primary or metastatic malignant neoplasm involving the esophagus. "Interestingly, other proteasome subunits were also expressed highly in EC and the elevated expression of PSMA2, PSMA5, PSMC6, PSMD5, PSMD10 indicated poor prognosis of EC patients respectively, which revealed a crucial role of 26S proteasome in esophageal cancer." (PMID 33897885, 2021).
gastric cancer (1 paper, 2025). A primary or metastatic malignant neoplasm involving the stomach. "To assess PSMC6's role in SYT4-driven gastric cancer progression, we co-transfected PSMC6 knockdown plasmids into SYT4-overexpressing (OE) cells." (PMID 41281742, 2025).
non-small cell lung carcinoma (1 paper, 2021). A group of at least three distinct histological types of lung cancer, including non-small cell squamous cell carcinoma, adenocarcinoma, and large cell carcinoma. "To uncover the functional role of PSMC6 in non-small-cell lung cancer (NSCLC), we performed CCK-8 assay to test the impact of PSMC6 on the cell proliferation." (PMID 34239933, 2021).
Obesity (1 paper, 2020). Accumulation of substantial excess body fat. "Another point to be discussed is that the present study is the first to identify an association between TPP2, PSMC6, ARL6IP1 and FAM49B genes with obesity." (PMID 32296077, 2020).
osteoporosis (1 paper, 2021). A condition of reduced bone mass, with decreased cortical thickness and a decrease in the number and size of the trabeculae of cancellous bone (but normal chemical composition), resulting in increased fracture incidence. "Psmc6 is a protein that is highly expressed in bone, and Psmc6 gene knockout increases bone mineral density (BMD) and PI3K protein phosphorylation in OVX osteoporosis mice and increases the protein level of cleaved caspase-3/-9." (PMID 34249129, 2021).
serous ovarian carcinoma (1 paper, 2025). "This hypothesis is corroborated by the evidence that, on the contrary to what observed in IGROV-1/Pt1, in serous ovarian carcinoma OVCAR-5/Pt cells the silencing of PSMC6 produced an increased activation of the MAPK pathway that likely favours cell survival counteracting cisplatin cytotoxicity." (PMID 40083690, 2025).
type 1 diabetes (1 paper, 2019). "Mutation in PSMC6 was important for progression of type 1 diabetes, but variation in this gene may be associated with the development of CAD." (PMID 31881747, 2019).
tumor (9 papers, 2020 to 2025). "In accordance with this finding, PSMC6 was associated with poor tumor differentiation." (PMID 34239933, 2021). "In accordance with this finding, PSMC6 was associated with poor tumor differentiation, suggesting that high expression of PSMC6 in patients with residual tumors or poor tumor differentiation indicates that PSMC6 may be associated with tumor recurrence." (PMID 34239933, 2021). "To evaluate the clinical significance of PSMC6 in LUAD, we compared the RNA or protein expression of PSMC6 of tumor samples with different clinical characteristics." (PMID 34239933, 2021). "Although the essential physiological function of PSMC6 protein may discourage from investigating PSMC6 druggability, the increased expression observed in our tumor model systems as compared to normal cells supports the interest of PSMC6 targeting." (PMID 40083690, 2025). "Consistently, PSMC6 RNA expression was higher in the LUAD patients with poorly differentiated tumor than those with well and moderately differentiated tumors, suggesting that PSMC6 was associated with the tumor differentiation." (PMID 34239933, 2021). "Consistently, the tumor cell invasion was also inhibited by the PSMC6 silence." (PMID 34239933, 2021). "Notably, PSMC6 was expressed higher in LUAD with residual tumor than those without (p value < 0.01), suggesting that PSMC6 was associated with residual tumor, which was considered a risk factor of tumor recurrence." (PMID 34239933, 2021). "Of note, PSMC6 silencing did not increase sensitivity to cisplatin in normal cells, where the expression of the gene is quite reduced as compared to tumor cells." (PMID 40083690, 2025). "The activity of WNT signaling was enhanced by the degradation of the AXIN complex via the proteasome, further demonstrating that the PSMC6 overexpression may activate WNT signaling via degrading AXIN protein, thereby promoting tumor progression." (PMID 34239933, 2021). "The correlation analysis revealed that the positively correlated genes with PSMC6 were highly enriched in WNT signaling-related pathways, demonstrating that the PSMC6 overexpression may activate WNT signaling via degrading the AXIN protein, thereby promoting tumor progression." (PMID 34239933, 2021). "We identified 39 Drosophila RNAi lines representing 29 human genes that strongly suppressed tumor growth (Strong Negative SSMD, 962—Rab11), while an additional 53 RNAi lines presenting 32 human genes moderately suppressed tumor growth (Moderate Negative SSMD, 561—PSMC6)." (PMID 32541798, 2020).
cancer (8 papers, 2021 to 2025). A tumor composed of atypical neoplastic, often pleomorphic cells that invade other tissues. "PSMC6 dysfunction has been confirmed in many cancers 30, and interfering with PSMC6 expression can suppress cell proliferation and promote apoptosis." (PMID 41281742, 2025). "PSMC6 was found expressed in several cancer cell lines with enhanced levels as compared to normal ovarian and fallopian tube cells." (PMID 40083690, 2025). "Previous studies showed that PSMC6 promotes osteoblast apoptosis and cancer cell proliferation, while PSMC2 inhibits apoptosis." (PMID 34329194, 2021). "Expectedly, the number of migratory cancer cells was obviously decreased in the cells with si-PSMC6 transfection than the negative controls." (PMID 34239933, 2021). "Interestingly, we discovered that PSMC genes were overexpressed in a subtype-specific manner: specifically, PSMC1, PSMC2, PSMC3, PSMC4 were highly expressed in the triple-negative subtype, PSMC5 in HER-2, and PSMC6 in luminal cancer." (PMID 34329194, 2021).
PSMC6 also shares sentences with these, for which no sentence is quoted: adenocarcinoma (1 paper); bladder cancer (1); cervical cancer (1); colon cancers (1); head and neck cancer (1); hemorrhage (1); infection (1); kidney renal cancer (1); liver cancer (1); melanoma (1); pancreatic cancer (1); Parkinson disease (1); pheochromocytoma (1); rhabdomyosarcoma (1).